TRIP4 (thyroid hormone receptor interactor 4)
Description:
Transcription coactivator which associates with nuclear receptors, transcriptional coactivators including EP300, CREBBP and NCOA1, and basal transcription factors like TBP and TFIIA to facilitate nuclear receptors-mediated transcription. May thereby play an important role in establishing distinct coactivator complexes under different cellular conditions. Plays a role in thyroid hormone receptor and estrogen receptor transactivation. Also involved in androgen receptor transactivation (By similarity). Plays a pivotal role in the transactivation of NF-kappa-B, SRF and AP1. Acts as a mediator of transrepression between nuclear receptor and either AP1 or NF-kappa-B. May play a role in the development of neuromuscular junction. May play a role in late myogenic differentiation (By similarity). Also functions as part of the RQC trigger (RQT) complex that activates the ribosome quality control (RQC) pathway, a pathway that degrades nascent peptide chains during problematic translation.
Synonyms: ASC-1; HsT17391; ZC2HC5; ASC1; MDCDC; SMABF1
Tractability: PROTAC: UniProt records ubiquitination sites on it; ubiquitination databases record sites on it; its protein half-life has been measured.
Gene: Protein-coding gene on chromosome 15 (64,387,748 to 64,455,305, forward strand). Ensembl gene ENSG00000103671.
Subcellular location: Nucleus; Cytoplasm, cytosol; Cytoplasm, cytoskeleton, microtubule organizing center, centrosome
Subcellular location (Human Protein Atlas): Nuclear bodies; Nucleoplasm
Pathways (Reactome):
Metabolism of proteins: ZNF598 and the Ribosome-associated Quality Trigger (RQT) complex dissociate a ribosome stalled on a no-go mRNA
Gene Ontology:
Molecular function: histone acetyltransferase binding; nuclear estrogen receptor binding; nuclear receptor binding; protease binding; protein binding; protein kinase binding; transcription coactivator activity; ubiquitin-like protein ligase binding; zinc ion binding
Biological process: estrogen receptor signaling pathway; positive regulation of DNA-templated transcription; regulation of DNA-templated transcription; rescue of stalled ribosome; ribosome disassembly; ribosome-associated ubiquitin-dependent protein catabolic process; regulation of myoblast differentiation
Cellular component: centrosome; cytoplasm; neuromuscular junction; nuclear body; nucleoplasm; nucleus; protein-containing complex; RQC-trigger complex; cytosol
Genetic constraint (gnomAD): Loss-of-function variants: 48 observed, 76.14 expected, observed/expected ratio (o/e) 0.63, 90% interval 0.5 to 0.8. The upper end of that interval is the gene's LOEUF score, 0.8, which puts it in group 3 of 6, group 1 being the genes least tolerant of losing a copy. Missense variants: 625 observed, 657.15 expected, observed/expected ratio (o/e) 0.95, 90% interval 0.89 to 1.02. Synonymous variants: 262 observed, 240.06 expected, observed/expected ratio (o/e) 1.09, 90% interval 0.99 to 1.21.
Homologues: Orthologues: macaque TRIP4 (99% identical), rabbit TRIP4 (92% identical), chimpanzee TRIP4 (91% identical), dog TRIP4 (90% identical), pig TRIP4 (89% identical), mouse Trip4 (89% identical), rat Trip4 (89% identical), guinea pig TRIP4 (88% identical), tropical clawed frog trip4 (58% identical), zebrafish trip4 (56% identical), Drosophila melanogaster CG11710 (33% identical), Caenorhabditis elegans trip-4 (23% identical).
Diseases named in the same sentence as TRIP4 in open-access papers:
TRIP4 is named in the same sentence as 26 diseases in open-access papers, as found by Europe PMC text mining. Sharing a sentence is not in itself a finding about the gene and the disease. The quoted sentences say what the papers report.
cervical cancer (6 papers, 2021 to 2024). A primary or metastatic malignant neoplasm involving the cervix. "Increased radiation resistance in cervical cancer may be caused by TRIP4 overexpression in tumor tissues and cancerous cells, which may encourage EMT and activate the PI3K/Akt and MAPK/ERK signaling pathways." (PMID 37175770, 2023). "It has been shown that TRIP4 is highly expressed in human melanoma, cervical cancer and colorectal cancer cell lines and tumor tissues, and that TRIP4 knockdown reduces proliferation, migration and invasion of tumor cells." (PMID 34204919, 2021). "Furthermore, in vivo studies have demonstrated that the knockdown of TRIP4 effectively inhibits cervical cancer growth and progression in a xenograft tumor model while concurrently reducing hTERT expression." (PMID 38651153, 2024). "TRIP4 overexpression in cervical cancer cells and tumor tissues may promote EMT and activate the PI3K/Akt and MAPK/ERK signaling pathways, enhancing radiation resistance in cervical cancer." (PMID 35897925, 2022). "The knockout of TRIP4 significantly impedes the proliferation and EMT of cervical cancer cells, which is concurrent with the deactivation of the PI3K/AKT and MAPK/ERK signaling pathways." (PMID 38651153, 2024). "Therefore, the targeting of TRIP4 in conjunction with hTERT and the PI3K/AKT pathway can serve as potential therapeutic strategies for overcoming radiotherapy resistance in cervical cancer." (PMID 38651153, 2024). "Mechanically, to explore whether solamargine regulates the Erk pathway by targeting a specific mRNA, we selected genes reported in recent years to regulate the Erk pathway in cervical cancer, including PBK, RACK1, CXCL3, TRIP4, and SEMA3C, for study." (PMID 36345403, 2022). "In order to investigate whether solamargine regulates the Erk signaling pathway by modulating target mRNAs, we screened out genes that regulate this pathway in cervical cancer including PBK, RACK1, CXCL3, TRIP4, and SEMA3C, which have been reported in the literature in recent years." (PMID 36345403, 2022).
spinal muscular atrophy (5 papers, 2018 to 2021). A motor neuron disease that affect the muscles, and characterized by muscle weakness and atrophy resulting from progressive degeneration and irreversible loss of the anterior horn cells in the spinal cord (i.e., lower motor neurons) and the brain stem nuclei. "Recessive variants in the TRIP4 gene have been associated with spinal muscular atrophy with bone fractures as well as a severe form of congenital muscular dystrophy." (PMID 34075209, 2021). "In 2016, truncating TRIP4 variants (AR transmission) were implicated in severe congenital myopathies and spinal muscular atrophy." (PMID 34440373, 2021). "Here we present the diagnostic journey of a patient with cerebellar hypoplasia, spinal muscular atrophy (PCH1-like) and congenital bone fractures, where we identified a homozygous stop-gain variant in the TRIP4 gene; the ninth case reported world-wide." (PMID 34075209, 2021). "Biallelic loss-of-function (LOF) pathogenic variants in TRIP4 and ASCC1 cause spinal muscular atrophy with congenital bone fractures (SMABF) 1 (MIM: 616866) and 2 (MIM: 616867)." (PMID 35047834, 2021). "This complex includes ASCC1 (associated with spinal muscular atrophy with congenital bone fractures 2), TRIP4 (associated with spinal muscular atrophy with congenital bone fractures 1), and ASCC2 (not yet associated with human disease)." (PMID 35047834, 2021). "Mutations of TRIP4 or ASCC1 have been reported both in patients with a congenital myopathy without any sign of motor neuron involvement, and in patients with a diagnosis of congenital motor neuron disease (Spinal Muscular Atrophy, SMA) associated with prenatal bone fractures." (PMID 34204919, 2021).
congenital myopathies (2 papers, 2021). "By contrast, TRIP4 mutations associated with a congenital myopathy phenotype lead to ASC-1 protein depletion." (PMID 34204919, 2021). "Thus, the most common phenotype associated hitherto with TRIP4 defects is a congenital myopathy termed ASC-1 related myopathy." (PMID 34204919, 2021).
malignant melanoma (2 papers, 2021 to 2025). "TRIP4, which is associated with malignant melanoma, was repressed by PTCH1 but to a lesser extent than PTCH1/FLNB double knockdown, perhaps reflecting the more aggressive nature of mBCC." (PMID 41373535, 2025).
schizophrenia (2 papers, 2023 to 2024). A major psychotic disorder characterized by abnormalities in the perception or expression of reality. "Among the six candidate genes, four (BDH2, CLDND1, GAS8, and TRIP4) displayed DTU events in all schizophrenia samples, while the other two genes (LARP4 and NVL) showed significant DTU events in specific subgroups." (PMID 38508189, 2024). "Amongst the six candidate genes, four (BDH2, CLDND1, GAS8, TRIP4) displayed DTU events in all schizophrenia samples, while the other two genes (LARP4, NVL) showed significant DTU events in specific subgroups." (PMID 37503064, 2023).
Alzheimer disease (1 paper, 2023). A progressive, neurodegenerative disease characterized by loss of function and death of nerve cells in several areas of the brain leading to loss of cognitive function such as memory and language. "TRIP4 gene has been identified as a candidate gene for Alzheimer’s disease susceptibility, and the CSNK1G1 gene may be a cause of syndromic developmental delay and autism spectrum disorder." (PMID 36658485, 2023).
cardiomyopathy (1 paper, 2021). A disease of the heart muscle or myocardium proper. "So far, 6 out of the 9 reported families with TRIP4 mutations presented clinically, electrophysiologically and histopathologically with a primary skeletal muscle phenotype, associated in some cases with cardiac muscle disease (cardiomyopathy), and had severe depletion or absence of ASC-1 protein." (PMID 34204919, 2021).
Cerebellar hypoplasia (1 paper, 2021). Cerebellar hypoplasia is a descriptive term implying a cerebellum with a reduced volume, but a normal shape and is stable over time. "We describe the diagnostic journey of a patient presenting with a cerebellar hypoplasia and SMA (PCH1-like) phenotype with bone fractures, in whom the exome reanalysis using the RD-Connect/Solve-RD pipeline identified a homozygous stop-gain variant in the TRIP4 gene." (PMID 34075209, 2021).
muscular dystrophies (1 paper, 2024). "The remaining six families had pathogenic variants in genes usually associated with muscular dystrophies (HNRNPDL, TOR1AIP1, SGCG, COL6A2, CAV3, TRIP4)." (PMID 38982518, 2024).
prenatal-onset spinal muscular atrophy with congenital bone fractures (1 paper, 2024). "Pathogenic variants in TRIP4 and ASCC1, subunits of activating signal co-integrator 1 (ASC-1), were shown to cause prenatal-onset spinal muscular atrophy with congenital bone fractures (SMABF) type 1 and 2, respectively (MIM#616866, MIM#616867)." (PMID 38274568, 2024).
rectal adenocarcinoma (1 paper, 2025). "Next, we analyzed the expression levels of ASCC3, ASCC1, ASCC2, and TRIP4 in TCGA rectal adenocarcinoma samples." (PMID 40881169, 2025).
tumor (6 papers, 2015 to 2025). "Increased cell proliferation was also confirmed in primary skin fibroblasts derived from TRIP4-mutant patients, which is consistent with the presence of skin abnormalities in ASC1-RM and indicates that ASC-1 is involved in cell cycle regulation in both fibroblasts and myogenic cells." (PMID 34204919, 2021). "The results slightly differed from those of TCGA, with ASCC3 and ASCC1 being more highly expressed in tumor tissue, while ASCC2 and TRIP4 were significantly expressed in normal tissue." (PMID 40881169, 2025). "TRIP4 mRNA expression was also upregulated significantly in TCGA HNSC-normal samples (****P<0.0001), and this expression was positively correlated with patient’s tumor grade (****P<0.0001)." (PMID 32275642, 2020). "We did not detect TMPRSS2-ERG gene fusion in this patient, however, we found that TMPRSS2 gene was fused with other partners including ETV4, TRIP4, and PNPO in the visit 1 patient tumor tissue, and all these TMPRSS2 involved fusion events were rediscovered in PDXs." (PMID 26695660, 2015).
TRIP4 also shares sentences with these, for which no sentence is quoted: breast carcinoma (2 papers); cancer (2); neuromuscular disease (2); autism spectrum disorder (1); colon cancer (1); colorectal cancer (1); congenital bone fractures (1); congenital muscular dystrophy (1); heart failure (1); Hip dysplasia (1); lung carcinoma (1); motor neuron disease (1); myopathy (1); renal cell carcinoma (1).